TNF (tumor necrosis factor)
Diseases named in the same sentence as TNF in open-access papers (continued):
Sharing a sentence is not in itself a finding about the gene and the disease.
Obesity (continued). "For instance, in humans, obesity is associated with chronic low-grade systemic inflammation, often marked by elevated cytokines like TNF-α, IL-6, and IL-1β." (PMID 40266905, 2025). "Obesity involves elevated levels of cortisol that indirectly encourage the secretion of TNF-α and IL6, two adipokines that cause inflammation, which increases metabolic dysfunctions." (PMID 40013194, 2025). "PA improves hypothalamic inflammatory states by reducing obesity-associated pro-inflammatory mediators (e.g., free fatty acids, TNFα, adiponectin, and advanced glycation end-products), thereby restoring leptin sensitivity and decreasing food intake." (PMID 41358225, 2025). "Chronic inflammation is linked to obesity, generating proinflammatory cytokines such as TNF-α, IL-6, IL-1β, and IL-18 that activate NF-kB." (PMID 40703753, 2025). "The production of IL-6 escalates with increasing body fat and the presence of IR, while elevated TNF α levels are associated with two key components of MetS: obesity and IR." (PMID 40310144, 2025). "Previous studies established that obesity-associated adipose inflammation is primarily driven by macrophage polarization (M1-type) and TNF-α/IL-1β overexpression, with CD8+ T-cell infiltration as an early trigger." (PMID 40725440, 2025). "Obesity is associated with a chronic low-grade pro-inflammatory state, where the increased levels of TNF-a, among others, suppress the transcription and secretion of adiponectin." (PMID 40559437, 2025). "Another critical factor contributing to increased ROS is TNF, which is linked to obesity and diabetes and is associated with insulin resistance and diabetes complications." (PMID 40718452, 2025). "On the other hand, as an endocrine organ, obesity secreted pro-inflammatory factors such as tumor necrosis factor α (TNF-α) and interleukin 6 (IL-6), which caused a long-term inflammatory state and affected the function of the kidney." (PMID 40230478, 2025). "The TNF-α gene encodes a pro-inflammatory cytokine involved in the pathogenesis of insulin resistance and obesity." (PMID 40732969, 2025). "Elevated pericardial adipose tissue volumes, such as in obesity, were associated with low adiponectin levels, low high-density lipoprotein, elevated TNF-alpha levels, and increased atherosclerotic lesions." (PMID 41155468, 2025). "In the setting of obesity, adipocytes are hypertrophied, and enlarged adipocytes release inflammatory and pathogenic adipocytokines, such as free fatty acids and tumor necrosis factor-α (TNFα), which induce insulin resistance." (PMID 40943240, 2025). "In this nested case–control study of Mediterranean individuals with overweight/obesity and MetS, higher baseline concentrations of IL-6, IL-1ra, TNFα, and IL-1β were associated with an increased risk of incident CKD after one-year follow-up." (PMID 40867871, 2025). "TNF-α is an inflammatory adipocytokine that is closely linked to obesity-induced insulin resistance and increases in response to accumulation of visceral fat." (PMID 40869040, 2025). "Monocyte chemoattractant protein-1 (MCP-1) produced by white adipocytes and tumour necrosis factor-α (TNF-α) produced by macrophages are pro-inflammatory cytokines and interact to form a pathogenic loop to exacerbate obesity-induced inflammation." (PMID 39803918, 2025). "Elevated levels of interleukins, and TNF-α, are also linked to the obesity-related asthma phenotype (Leiria, Martins, and Saad, 2015; Wang and Hu, 2022)." (PMID 40242447, 2025). "Probiotics have demonstrated potential in modulating levels of HDL-C, LDL-C, lipocalin, leptin, and TNF-α in overweight or obese children, potentially alleviating metabolic symptoms associated with obesity." (PMID 40242164, 2025). "For instance, C57BL/6 mice subjected to high-fat diets exhibit obesity and demonstrate increased levels of pro-inflammatory cytokines like TNF-α and interleukin-6 (IL-6), which are associated with liver inflammation and damage." (PMID 41001122, 2025).
Obesity (continued). "Obesity is associated with increased levels of interleukin-6 (IL-6) and tumor necrosis factor-α (TNF-α)." (PMID 40909922, 2025). "Smoking is associated with radiographic progression of EA, and smoking and obesity are associated with reduced TNF inhibitor response." (PMID 41376896, 2025). "GSDF induces a decrease in the expression of inflammatory proteins like IL-1β and TNF-α in tissues through its regulatory action, inhibits the occurrence of tissue inflammation, and improves the damage to eWAT caused by obesity." (PMID 40428495, 2025). "This study provides novel insights into the relationship between the TNF-α -308 G/A polymorphism, dietary antioxidants, and nutrient–gene interactions in the regulation of insulin levels among Spanish adults with obesity." (PMID 40732969, 2025). "Among the key lipid metabolites, 12,13-DiHOME—secreted by brown adipose tissue—was significantly associated with TNFα expression and is implicated in metabolic disorders such as obesity and dyslipidemia." (PMID 40943362, 2025). "Biomarkers such as C-reactive protein, IL-6 and TNF can indicate the presence of systemic inflammation associated with obesity." (PMID 40553147, 2025). "In cases of obesity, adipose tissue releases pro-inflammatory cytokines such as TNF-α, IL-6, and CRP, which play a role in causing liver inflammation and injury." (PMID 41007669, 2025). "TNF-α expression was increased in the adipose tissue of type 2 diabetic individuals and db/db mice, and the loss of TNF-α function protected against obesity-induced insulin resistance." (PMID 40286055, 2025). "Although TNF-α is a well-known pro-inflammatory cytokine associated with obesity, TNF-β also plays a significant role in inflammatory processes." (PMID 40519917, 2025). "Overexpression of TNF‐α has a strong correlation with the pathogenesis of numerous chronic inflammatory diseases, such as obesity‐associated T2DM82 and rheumatoid arthritis." (PMID 39355932, 2025). "Inflammatory factors within adipose tissue are linked to the mechanisms of obesity-related metabolic dysfunction, with elevated levels of C-reactive protein, TNF-α, and interleukin (IL)-6 accelerating the progression of chronic metabolic diseases in obesity." (PMID 40673005, 2025). "Obesity is inherently linked to chronic inflammation, characterized by an excess of key inflammatory mediators, including tumor necrosis factor-alpha (TNF-α) and others." (PMID 41018420, 2025). "Compared with the model group, electroacupuncture further controlled obesity- and inflammation-associated factors [e.g., reduced leptin, tumor necrosis factor-α (TNF-α), and interleukin-1β (IL-1β)]." (PMID 40776915, 2025). "One well-known pro-inflammatory cytokine is TNFα, which has been highly associated with obesity and T2D given its implications for insulin signaling and insulin resistance development." (PMID 40723425, 2025). "Inflammation assessment showed that WMSZY markedly suppressed TNF-α and IL-1β expression in eWAT, both of which are closely associated with obesity-related chronic low-grade inflammation." (PMID 41194880, 2025). "Chronic inflammation associated with obesity elevates pro-inflammatory cytokines like TNF-alpha and IL-6, exacerbating oxidative stress and DNA damage in sperm cells." (PMID 40008399, 2025). "Further, in experimental models of obesity and diabetes, TNFα is abnormally high in adipose tissues and is associated with insulin resistance." (PMID 39269560, 2025). "One commonly proposed mechanism of obesity-related immune dysfunction is the underlying chronic inflammatory state of obesity, with increased levels of inflammatory cytokines including TNFα, IL6, and leptin." (PMID 40386706, 2025). "Elevated cytokines, such as TNF-α and IL-6, impair tissue recovery, while obesity-associated dyslipidemia amplifies ROS-induced cellular damage." (PMID 40282189, 2025).
Obesity (continued). "On the other hand, in an extensive systematic review and metanalysis of RCT studying the effect of dietary weight loss intervention on IL-6 and TNF-α in adults with obesity, only IL-6 was reported to be significantly reduced after at least 5% of weight loss." (PMID 40430061, 2025). "HFD causes obesity, increases inflammatory cytokines (e.g., TNF-α, IL-6), and promotes lipid accumulation in the liver, which impairs insulin receptor function." (PMID 40689212, 2025). "Due to the chronic low-grade inflammation that characterizes this syndrome, elevated TNF-α levels are associated with hyperandrogenism, the development of insulin resistance and obesity because TNF-α interferes with insulin signaling." (PMID 40647668, 2025). "Obesity, a major risk factor, is associated with elevated pro-inflammatory markers (TNF-α, IL-6) and reduced anti-inflammatory IL-10 and adiponectin." (PMID 40941639, 2025). "Obesity is associated with increased production of reactive oxygen species (ROS) and inflammatory adipokines such as resistin, tumor necrosis factor alpha (TNFα), and interleukin 6 (IL-6), as well as a reduction in anti-inflammatory adipokines (adiponectin)." (PMID 39334752, 2024). "Elevated TNF-α levels in males further highlight the greater inflammatory state associated with obesity in men." (PMID 39149648, 2024). "Compared with the high-calorie diet groups, phentermine groups, and orlistat groups, Qu can significantly inhibit the expression of pro-inflammatory genes such as IL-6, IL-1β, IL-18, and TNF-α, thereby alleviating the inflammatory state caused by obesity." (PMID 39712006, 2024). "Although many cytokines and chemokines are involved in obesity-induced inflammation, TNF-α, IFN-γ, IL-6, and especially IL-1β have been closely linked to systemic insulin resistance." (PMID 39606781, 2024). "Empagliflozin attenuates chronic inflammation associated with obesity by reducing plasma TNF-α levels." (PMID 38685954, 2024). "Several obesity-associated events, including tumor necrosis factor α (TNFα)-induced inflammation, hypoxia, and palmitic acid (PA, 16:0) exposure, promote EV secretion from these cells." (PMID 38965596, 2024). "TNFα, IL-1β, IL-6, or IL-8 are proinflammatory cytokines that are considered obesity-linked inflammatory cytokines, predominantly in the abdominal fatty tissue." (PMID 39057082, 2024). "While obesity was associated with upregulation of many effector molecules, TNF-α, COX-2 and IL-6 expression showed the strongest responses." (PMID 38672413, 2024). "Obesity is also associated with the secretion of pro-inflammatory cytokines, such as interleukin-6 (IL-6) and tumor necrosis factor alpha (TNFα), as well as adipokines like leptin." (PMID 39767718, 2024). "Overweight/obesity was also linked to increased plasma levels of IL-5, IL-17A, IL-22, IL-33, TNF-α, and leptin and decreased levels of IL-10." (PMID 39902293, 2024). "Some studies also found that elevated levels of pro-inflammatory cytokines, such as IL-1β, IL-6, and TNF-α, associated with obesity can impair sleep architecture and promote sleep disturbances." (PMID 39267856, 2024). "Leptin, as an obesity-associated hormone present in co-cultured CMs, can reduce TNF-α levels through positive feedback." (PMID 39072314, 2024). "Several immune molecules have been implicated in the pathogenesis of obesity, such as TNFα, which shows elevated plasma levels in obese patients." (PMID 39351493, 2024). "Obesity is associated with systemic low-grade inflammation with elevated levels of pro-inflammatory cytokines such as IL-6 and TNF-α." (PMID 39902293, 2024). "It is known that adipocyte hypertrophy and hyperplasia and increased pro-inflammatory cytokines, such as IL-6 and TNF-α, are strongly related to obesity, which is one of the causative agents of chronic inflammation." (PMID 38470620, 2024).
Obesity (continued). "In chronic renal failure related to obesity, TNF-α, IL-1β, and IL-6 genetic overexpression was associated with chronic inflammation in adipose tissue." (PMID 39274918, 2024). "Obesity causes adipocytes to secrete a variety of inflammatory factors, including tumor necrosis factor-α (TNF-α), interleukin-6 (IL-6), and C-reactive protein (CRP)." (PMID 38707891, 2024). "Obesity increases serum TNF-α in both humans and mice, and a polymorphism in the promoter region of the human gene (TNF), which leads to increased TNF expression, is coupled to a stronger association of obesity with asthma, particularly non-atopic asthma." (PMID 38878250, 2024). "Although APP is predominantly linked to the pathophysiology of Alzheimer’s disease, a recent report pointed out its association with obesity phenotypes such as insulin resistance and inflammation, which are regulated by tumor necrosis factor α (TNF-α)." (PMID 39329749, 2024). "Serum TNF-α and IL-1β levels of rats were also analyzed in order to evaluate chronic inflammation associated with obesity." (PMID 39055496, 2024). "Obesity is associated with an inflammatory status characterized by high concentrations of inflammatory cytokines such as IL-6 and TNF-α, which can affect bone and muscle tissues." (PMID 39902393, 2024). "Genetic polymorphisms of the TNF-α gene were found to be significantly associated with the risk of obesity in certain populations, further confirming the association with the condition." (PMID 39275140, 2024). "Insulin resistance is often associated with obesity, which triggers a low-grade inflammatory response involving pro-inflammatory mediators such as TNF-α, IL-17, and NF-κB." (PMID 39458839, 2024). "TNF-α causes alterations in specific metabolic pathways, including obesity and hypercholesteremia, which worsen and accelerate the progression of AD." (PMID 38397814, 2024). "Chronic inflammation is induced by the continuous production of TNF-α and is the fundamental cause of diseases like obesity, dyslipidaemia, diabetes, heart and brain diseases, autoimmune diseases, Alzheimer’s disease, and cancer." (PMID 38396804, 2024). "Obesity is associated with a chronic, low-grade inflammatory state, characterized by elevated levels of pro-inflammatory cytokines such as TNF-α, IL-6, and CRP." (PMID 39468643, 2024). "It is known that obesity favors the release of pro-inflammatory cytokines such as tumor necrosis factor α and Interleukin-6, which are linked to the development of inflammation, and the onset of cancer." (PMID 38398110, 2024). "IR can instigate an upsurge of inflammatory cytokines associated with obesity, including IL-1β, IL-2, IL-4, IL-5, IL-6, IL-8, tumor necrosis factor-α, and interferon, which have been robustly linked to the development of PAH." (PMID 38702735, 2024). "Some studies demonstrated consistently higher levels of TNF-α than IL-6 in severe COVID-19 patients and those with underlying comorbidities such as obesity, chronic heart failure, and hypertension." (PMID 39518964, 2024). "Inflammatory processes associated with obesity and metabolic syndrome, including the release of pro-inflammatory cytokines like TNF-α and IL-6, create a tumor-promoting environment that enhances cancer cell proliferation, invasion, and resistance to apoptosis." (PMID 39518104, 2024). "Risk factors for GD, such as obesity, are associated with increased numbers of resident adipose tissue macrophages that secrete pro-inflammatory cytokines, including TNF-α, IL-6, and IL-1β." (PMID 39456486, 2024). "In this study, DNA methylation of TNF-α profiles was significant associated with obesity, metabolic syndrome components (abnormal waist circumference, TG, and FPG), and dietary factors." (PMID 38542788, 2024).
Obesity (continued). "The level of plasma TNF-α has been shown to correlate with obesity severity and is linked to obesity-induced insulin resistance, and lipid-derived or myogenic TNF-α contributes to peripheral tissue insulin resistance induced by adiposity." (PMID 40302954, 2024). "Proinflammatory cytokines like TNFα, interleukin-1β (IL-1β), and IL-6, produced primarily by macrophages infiltrating adipose tissue due to obesity, are linked to insulin resistance and MetS features." (PMID 38999869, 2024). "Elevated leptin levels in obesity are associated with increased production of inflammatory cytokines, such as TNF-α and IL-6, which further contribute to chronic low-grade inflammation seen in obesity and metabolic syndrome." (PMID 39700087, 2024). "TNF-α is essential in the hormonal adjustments linked to metabolic disorders caused by obesity and can trigger the synthesis of other inflammatory cytokines." (PMID 39149648, 2024). "While obesity is associated with increased production of pro‐inflammatory cytokines like TNFα and IL1β, it is less clear how age and duration of HFD affect inflammation in the visceral adipose tissue of female mice." (PMID 39230054, 2024). "This suggests that the effect of BMI on PASC risk is not only mediated by inflammation (as indicated by the association of obesity at COVID-19 onset with raised TNFα, sCD163 and CRP at 21–24 weeks), but also by additional physiological and metabolic processes." (PMID 39008486, 2024). "It has also been demonstrated to bind to PPARγ and reduce obesity-associated inflammation, as well as reduce pro-inflammatory cytokine production by inhibiting NF-κB and TNF-α activation in a carrageenan-induced inflammation murine model." (PMID 39458839, 2024). "The accumulation of visceral adipose tissue macrophages is also a hallmark of obesity, and these cells secrete pro-inflammatory cytokines like TNF, IL-6, and IL-1ß, driving systemic, chronic, low-grade inflammation." (PMID 39050851, 2024). "Obesity is associated with a low-grade chronic inflammatory process characterized by higher circulating TNFα levels, thus contributing to insulin resistance." (PMID 38953241, 2024). "During pregnancy, elevated levels of circulating cytokines (TNF-a and IL-6) are thought to drive obesity-associated metabolic inflammation." (PMID 38145995, 2024). "The aim of the study was to analyse the circulating miRNA 423-5p and miRNA 128-1 levels and their association with cytokines (TNF-α and IL-6) before intervention with adults with obesity and lean adults of the 18–23 age group." (PMID 38541185, 2024). "Clinical studies demonstrated that serum levels of TNF-α are elevated in patients with obesity, and decrease with weight loss." (PMID 38572445, 2024). "Increased levels of TNF-α (Tumor necrosis factor α) are the major cause of the obesity-induced decrease in PGC1α expression." (PMID 38928386, 2024). "Both T2DM and obesity are also associated with low chronic inflammation as evidenced by the release of pro-inflammatory cytokines interleukin-1β (IL-1β) and tumor necrosis factor-α (TNF-α) that leads to more osteoclastogenesis and adipogenesis." (PMID 39273348, 2024). "The second point to consider is that obesity has the potential to cause pathophysiologic changes, including inflammatory reactions and the overexpression of tumor necrosis factor (TNF), which are significant risk factors for the development of CVD." (PMID 38474832, 2024). "Obesity is associated with autoimmunity through an increase in pro-inflammatory cytokines (IL-6, TNF alpha, and IL-17) and more than 50 adipokines as well as changes in the expression of the apoptotic inhibitor of macrophages." (PMID 38775508, 2024). "Obesity and asthma have been linked through chronic systemic inflammation driven by adipokines such as leptin, adiponectin, TNF-α, monocyte chemotactic protein-1 (MCP-1), and IL-6." (PMID 40474934, 2024).